NCAPG (non-SMC condensin I complex subunit G)
Diseases named in the same sentence as NCAPG in open-access papers (continued):
Sharing a sentence is not in itself a finding about the gene and the disease.
liver cancer (13 papers, 2019 to 2025). An epithelial or non-epithelial malignant neoplasm that arises from the liver. "NCAPG associated with cell proliferation and migration of liver cancer cells, but this gene might be linked with cell proliferation and migration of pituitary prolactinoma cells." (PMID 33709028, 2021). "Through bioinformatics analysis, it was found that NCAPG is also a key gene involved in the occurrence and development of liver cancer." (PMID 35864529, 2022). "High expression of RRM2, MADAL1, MELK, NCAPG and ASPM were associated with poor OS for liver cancer patients." (PMID 35928445, 2022). "To explore the role of NCAPG in the proliferation of liver cancer cells, we first stably transfected an NCAPG overexpression plasmid (pcDNA3.1( +)-NCAPG) into MHCC97H and HCCLM3 cells." (PMID 35864529, 2022). "In summary, these data indicated that the effects of NCAPG on the proliferation of liver cancer cells are achieved through the PI3K-AKT signalling pathway and are closely related to PTEN." (PMID 35864529, 2022). "Enrichment analysis with DisGeNET showed that the role of NCAPG in liver cancer is more important than that in other diseases." (PMID 35864529, 2022). "Through transcriptome sequencing, we found that NCAPG affects the proliferation of liver cancer cells, while proteomic analysis helped us to find that NCAPG regulates the key PTEN protein CKII." (PMID 35864529, 2022). "The results of the differential gene expression analysis of liver cancer cells with NCAPG downregulation indicated that the expression of PTEN was significantly increased compared with that in the control cells (P < 0.001)." (PMID 35864529, 2022). "These complementary methods based on big data improve the accuracy of the study design and can help us to better show the involvement of NCAPG in the promotion of liver cancer." (PMID 35864529, 2022). "Previous studies reported that NCAPG is associated with the proliferation and migration of HCC cells and poor prognoses in castration-resistant prostate and liver cancers." (PMID 31892156, 2019). "NCAPG expression was initially found to be correlated with the prognosis of liver cancer." (PMID 36996493, 2023). "In our previous studies, we confirmed that NCAPG has abnormally high expression in liver cancer." (PMID 35864529, 2022). "In previous studies, the expression of NCAPG in various liver cancer cells was screened." (PMID 35864529, 2022). "In addition, IHC analysis revealed the same results; that is, NCAPG is highly expressed in liver cancer tissues." (PMID 35864529, 2022). "In addition, our experimental data showed that NCAPG overexpression promotes the proliferation of liver cancer cells, while NCAPG silencing inhibits the proliferation of liver cancer cells." (PMID 35864529, 2022). "In addition, they also find that NCAPG could serve as a promoter of invasion and metastasis of liver cancer." (PMID 33927744, 2021). "Studies have shown that NCAPG, as a homo-family protein of NCAPD3, can affect the proliferation and apoptosis of liver cancer cells through the PI3K/AKT signaling pathway, which is comparable with what we discovered." (PMID 38566039, 2024). "Then, immunohistochemistry staining validated from the Human Protein Atlas database showed that ZWINT, NCAPG and CENPF protein expression were strongly upregulated in liver cancer tissues compared with normal tissues." (PMID 31410310, 2019). "TTo determine whether NCAPG is overexpressed in HCC, we examined NCAPG expression in 85 pairs of primary liver cancer tissues and the corresponding normal adjacent tissues." (PMID 35864529, 2022). "The Western blot results showed that compared with the adjacent nontumor tissues, the primary liver cancer tissues exhibited significant overexpression of NCAPG." (PMID 35864529, 2022). "The results showed that NCAPG was significantly overexpressed in most liver cancer tissues compared with the adjacent nontumor control tissues." (PMID 35864529, 2022).
liver cancer (continued). "To reveal whether NCAPG affects the proliferation of HCC through PTEN and the PI3K-AKT pathway, we investigated whether the PI3K-AKT pathway inhibitor MK2206 could attenuate the proliferation of liver cancer." (PMID 35864529, 2022). "In conclusion, for the first time, our research revealed the molecular mechanism by which NCAPG promotes liver cancer proliferation, namely, NCAPG inhibits PTEN through interaction with CKII and then activates the PI3K-AKT pathway to promote the proliferation of liver cancer." (PMID 35864529, 2022).
colorectal cancer (11 papers, 2022 to 2025). A primary or metastatic malignant neoplasm that affects the colon or rectum. "Specifically, Ding-Ping Sun’s research revealed that NCAPG is highly expressed in colorectal cancer (CRC) tissues, and its downregulation inhibits CRC cell proliferation, migration, and invasion by interfering with the G2/M to G1 cell cycle transition." (PMID 40406126, 2025). "Shi et al21 reported that NCAPG fosters proliferation, migration, and invasion of colorectal cancer cells through the Wnt/β‐catenin signaling pathway by binding to β‐catenin." (PMID 37553792, 2023). "NCAPG facilitated colorectal cancer cell proliferation, migration, invasion, and EMT by activation of the Wnt/β-catenin signaling pathway." (PMID 36362041, 2022).
melanoma (11 papers, 2007 to 2025). A malignant, usually aggressive tumor composed of atypical, neoplastic melanocytes. "Among the genes that were downregulated by silencing this deacetylase are those that have been positively correlated with melanoma aggressiveness (e.g., NCAPG, CDKN2C, GINS1, and DHFR are all downregulated in the SSW30 clone)." (PMID 31091806, 2019). "NCAPG in cancers has been less well studied, but it is overexpressed in melanomas and downregulated in out-of-niche primary tumor cells from multiple myelomas and acute myeloid leukemias." (PMID 26933822, 2016). "The NCAPG expression is upregulated in more aggressive metastatic melanomas than in less aggressive primary melanomas." (PMID 19653884, 2009). "Likewise, NCAPG (i.e. hCAP-G) is also upregulated in melanomas." (PMID 29467813, 2018).
ovarian carcinoma (10 papers, 2018 to 2024). A malignant neoplasm originating from the surface ovarian epithelium. "Analysis using GEPIA and KM plotter database showed NCAPG was upregulated in ovarian cancer and negatively associated with the survival of OC patients." (PMID 35986371, 2022). "Similarly, high expression of NCAPG is associated with poor prognosis in ovarian cancer." (PMID 35211508, 2021). "In the present study, we assessed tumor specimens derived from ovarian cancer patients for NCAPG protein expression using immunohistochemistry." (PMID 35986371, 2022). "In summary, our results demonstrated for the first time the overexpression of NCAPG in ovarian cancer." (PMID 35986371, 2022). "Our results suggest that NCAPG exhibits an important role in the development and progression of ovarian cancer and implicates NCAPG as a potential therapeutic target in ovarian cancer." (PMID 35986371, 2022). "To perform the function of NCAPG in ovarian cancer, we used shRNA plasmid to knock down NCAPG in two ovarian cancer cell lines, SKOV3 and OVCAR3." (PMID 35986371, 2022). "To confirm the function of NCAPG in OC, we knocked down NCAPG expression in ovarian cancer OVCAR3 and SKOV3 cells with shRNA plasmid vectors." (PMID 35986371, 2022). "We then sought to explore the molecular mechanisms through which NCAPG knockdown constrains the malignancy of ovarian cancer." (PMID 35986371, 2022). "Studies have shown that interference with NCAPG can inhibit the growth, proliferation and invasion of ovarian cancer cells (OC) by promoting the activation of the p38 MAPK signaling pathway, and it blocks the cell cycle and promotes apoptosis in the G2 and S phases." (PMID 39545257, 2024). "NCAPG mRNA expression increased significantly in ovarian cancer." (PMID 35986371, 2022). "In addition, we observed that the expressions of NCAPG in ovarian cancer patients showed a significantly relative relationship with the histological type, FIGO stage, lymph node metastasis, and tumor grade." (PMID 35986371, 2022). "The mRNA expression, overall survival, and disease-free survival of NCAPG in ovarian cancer were analyzed by GEPIA and KM plotter database, and the expression levels of NCAPG in OC tissues and cell lines were determined by qPCR and immunohistochemistry analysis." (PMID 35986371, 2022). "Furthermore, high expression of NCAPG are relevant to poor prognosis in ovarian cancer and hepatic cancer." (PMID 35963640, 2022). "Finally, western blot assays were performed to detect the mechanism of NCAPG in ovarian cancer." (PMID 35986371, 2022). "However, the roles of NCAPG in ovarian cancer remain unclear." (PMID 35986371, 2022). "The protein expressions of 5 hub genes (CDK1, TOP2A, CDC20, NCAPG, and MELK) are significantly up-regulated in ovarian cancer compared to normal tissues." (PMID 30453999, 2018). "Moreover, qRT-PCR analysis of two ovarian cancer cell lines (SKOV3 and OVCAR3) and human ovarian epithelial cell line IOSE80 showed that NCAPG mRNA increased in the OC cells." (PMID 35986371, 2022). "However, no study has clarified the role of NCAPG in ovarian cancer." (PMID 35986371, 2022). "Notably, we illuminated that NCAPG knockdown may inhibit the development of ovarian cancer via the p38 MAPK signaling pathway, which suggests that NCAPG may be a prognostic therapeutic target in ovarian cancer." (PMID 35986371, 2022).
endometrial cancer (9 papers, 2022 to 2025). Primary or metastatic malignant neoplasm involving the endometrium (mucous membrane that lines the endometrial cavity). "NCAPG promotes the progression of endometrial cancer (EC) through PI3K-AKT pathway and has potential as a novel tumor marker." (PMID 39744480, 2025). "NCAPG silencing inhibited cell proliferation and induced apoptosis in endometrial cancer cells via inhibiting the Wnt/β-catenin pathway." (PMID 36439516, 2022). "Silencing of NCAPG was also shown to reduce endometrial cancer cell growth by inactivating the Wnt/β-catenin signaling pathway." (PMID 35292013, 2022).
lung adenocarcinoma (9 papers, 2020 to 2025). A carcinoma that arises from the lung and is characterized by the presence of malignant glandular epithelial cells. "High NCAPG expression levels are a prognostic marker for lung adenocarcinoma, and its high expression was negatively correlated with overall patient survival time." (PMID 35292013, 2022). "In lung adenocarcinoma, NCAPG promoted cell proliferation and migration through transforming growth factor β signaling pathway activation." (PMID 35211510, 2022). "Results from next-generation sequencing comparing expression levels from tumor and adjacent normal tissues have suggested that NCAPG could be used as a prognostic biomarker for liver and lung adenocarcinoma." (PMID 35292013, 2022). "This study aimed to clarify the role of the non-SMC condensin I complex, subunit G (NCAPG) in lung adenocarcinoma (LUAD), explore the mechanisms of its progression, and lay the foundation for the search for new biological markers." (PMID 34419073, 2021).
non-small cell lung carcinoma (7 papers, 2022 to 2025). A group of at least three distinct histological types of lung cancer, including non-small cell squamous cell carcinoma, adenocarcinoma, and large cell carcinoma. "High levels of NCAPG have been associated with poor prognosis in patients with prostate cancer and non-small cell lung cancer (NSCLC)." (PMID 35280743, 2022). "NCAPG-driven CDK1 facilitates the malignant progression of non-small cell lung cancer through ERK signaling activation." (PMID 40746552, 2025). "Existing literature suggests that NCAPG promotes oncogenesis in non-small cell lung cancer cells by upregulating LGALS1 expression." (PMID 37335105, 2023).
renal cell carcinoma (6 papers, 2022 to 2025). "Finally, we further explore NCAPG expression in normal kidney cell HK-2 and renal cell carcinoma cell HTB-47 and CRL-1932 cells, and the results showed that NCAPG expression was significantly elevated in renal cell carcinoma cells compared with the normal kidney cell." (PMID 35601741, 2022).
lymph node metastasis (4 papers, 2022 to 2023). "Univariate Cox regression analysis indicated that tumor diameter, pathological classification, depth of invasion, lymph node metastasis, TNM stage, and Gal1 and NCAPG expression were associated with OS in GC patients (all P < 0.001)." (PMID 37335105, 2023). "Subgroup analysis showed that in some cancers, upregulation of NCAPG was correlated with age, distant metastasis, lymph node metastasis, TNM stage, relapse, differentiation, clinical stage, and vascular invasion." (PMID 36996493, 2023). "The results showed that the expression of NCAPG was related to the age, lymph node metastasis, and stage of tumor patients." (PMID 36996493, 2023). "Moreover, the expression level of NCAPG in patients is related to clinical stage(p = 0.0392), T factor(p = 0.0000), lymph node metastasis(p = 0.008) and distance metastasis(p = 0.0135)." (PMID 35254214, 2022).
renal clear cell carcinoma (4 papers, 2022 to 2025). "We further found that the expression of NCAPG was associated with the overall survival and disease-free survival of renal clear cell carcinoma, and these patients with higher expression of NCAPG have a poorer OS and DFS." (PMID 35601741, 2022). "We further found that the expression of NCAPG was associated tightly with the prognosis and progression of renal clear cell carcinoma." (PMID 35601741, 2022). "In summary, we preliminary proposed that NCAPG promoted the proliferation of renal clear cell carcinoma via mediating CDK1; however, the conclusion needs further verification and consolidation." (PMID 35601741, 2022). "And we analyzed the correlation between NCAPG and CDK1 by immunohistochemical staining among the 72 cases with renal clear cell carcinoma; the results showed that NCAPG is related with CDK1." (PMID 35601741, 2022). "We further explored the effects of knockdown NCAPG on the proliferation and progression of renal clear cell carcinoma; we performed CCK-8 assay and colony forming assay to observe the change of proliferation ability in HTB-47 and CRL-1932 cells." (PMID 35601741, 2022). "To further explore the expression of NCAPG in renal clear cell carcinoma and the normal tissue, we extracted the differential expression of NCAPG in renal clear cell carcinoma and the normal tissue from GEPIA online database." (PMID 35601741, 2022). "NCAPG was upregulated in renal clear cell carcinoma, which was related with tumor size and overall survival." (PMID 35601741, 2022). "In this study, we found that NCAPG was upregulated in several cancers, including in renal clear cell carcinoma." (PMID 35601741, 2022). "We observed the differential expression of NCAPG in several cancers from GEPIA online database, and the expression of NCAPG in renal clear cell carcinoma and normal tissue was compared and further verified by IHC assay." (PMID 35601741, 2022). "There were so many articles indicated that NCAPG was upregulated in various cancers and promoted the proliferation and progression, which further consolidate our results of NCAPG promoting the proliferation of renal clear cell carcinoma." (PMID 35601741, 2022). "We still found that the expression of NCAPG was associated with the tumor size of renal clear cell carcinoma by analyzing the relationship between NCAPG and several clinicopathological parameters among 72 patients with renal clear cell carcinoma." (PMID 35601741, 2022). "NCAPG was upregulated in renal clear cell carcinoma compared with the normal tissue, and the expression of NCAPG was associated with the clinical prognosis of pancreatic cancer especially with tumor size (P = 0.010)." (PMID 35601741, 2022). "To further verify the conclusion from the database, we collected 72 paired tissue of patients with renal clear cell carcinoma and conducted immunohistochemical staining to observe the expression of NCAPG." (PMID 35601741, 2022). "Next, we explore the correlation between the expression of NCAPG and several common clinicopathological parameters of renal clear cell carcinoma, including age, gender, tumor grade, and tumor size." (PMID 35601741, 2022). "The results showed that the expression of NCAPG was significantly higher in renal clear cell carcinoma compared with the normal tissue." (PMID 35601741, 2022). "To further explore the effects of NCAPG in the proliferation and progression of renal clear cell carcinoma, we knockdown NCAPG and found that NCAPG could promote significantly the proliferation and progression of renal clear cell carcinoma." (PMID 35601741, 2022). "We further found that NCAPG shRNA also promotes the apoptosis rate of HTB-47 and CRL-1932 cells compared with the control group, which further implied that NCAPG regulated the progression of renal clear cell cancer which depend not only proliferation but also apoptosis." (PMID 35601741, 2022).